CDC42 (cell division cycle 42)
Diseases named in the same sentence as CDC42 in open-access papers (continued):
Sharing a sentence is not in itself a finding about the gene and the disease.
breast carcinoma (continued). "To gain a more comprehensive understanding of the interplay between OA and cell protrusions, and their combined impact on breast cancer cell migration, we conducted wound healing assays in the presence of the two distinct inhibitors for Cdc42 and the Arp2/3 complex (ML141 and CK666)." (PMID 38612766, 2024). "In turn, our data suggest that the role of Rac1 and Cdc42 in controlling the redox balance in breast cancer cells might be complex." (PMID 39062543, 2024). "To determine whether Rac and Cdc42 inhibitors affect leukocyte migration in vivo, we quantified leukocytes by immunofluorescence or flow cytometry in tumors or spleen in preclinical breast cancer mouse models." (PMID 37397366, 2023). "In this work, we investigate the regulation of Rac1 and Cdc42 in the epithelial breast cancer cell line (MDA-MB-231) during cell membrane ruffling, a phenomenon that is characterized by the formation and retraction of actin-rich membrane protrusions at the periphery of a spread cell." (PMID 37371108, 2023). "Since leukocytes are known to promote metastasis via cross-talk signaling with cancer cells, the observation of reduced macrophage and neutrophil counts in mammary tumors following Rac inhibition validates a dual role for Rac/Cdc42 inhibitors in tumor malignancy." (PMID 37397366, 2023). "NCGC00131308 prevented the increase in active Cdc42 induced by EGF in breast carcinoma cells." (PMID 36253497, 2022). "In breast cancer, Rac and Cdc42 dysregulation can be attributed to overexpression due to gene amplification and mRNA upregulation, hyperactivity via the upstream regulators guanine nucleotide exchange factors (GEF), overexpression of oncogenic cell surface receptors, or a combination of these." (PMID 36861094, 2022). "At later stages of breast cancer development, increased CDC42 expression could promote cancer progression via its effects on cell cycle progression and invasion." (PMID 35087170, 2022). "CDC42 can play an important role as a gene for targeted therapy of breast cancer." (PMID 35280773, 2022). "A decrease in the transcription levels of human invasion signature (HIS) genes (ARHGDIB, CAPZA2, PHACTR2, CDC42, XRCC5, and CAV1) has been also demonstrated by real-time PCR, with high expression of these genes being a hallmark of actively metastasizing breast cancer cells." (PMID 36143471, 2022). "Based on the cross-talk of integrins and FAK and integrin-mediated regulation of the activity of Rho family proteins in cell migration, the expression of Rho family proteins, including Rac1, RhoA, Cdc42, and integrins, is detected in breast cancer cells after CuB exposure." (PMID 36362132, 2022). "Importantly, PDLIM1 combines with α-actinin-4 to form a PDLIM1-α-actinin complex, thereby promoting the activation of Cdc42, which is a key factor in regulating cell polarity and migration of breast cancer cells." (PMID 34396044, 2021). "Thus, these abnormalities, which can sometimes progress to ductal carcinoma in situ and breast cancer, mirror the effects of lateral Cdc42 activation." (PMID 33646271, 2021). "Based on these findings, targeting PDLIM1-α-actinin-Cdc42 axis may have a potential for inhibiting breast cancer metastasis and is worthy of further investigation." (PMID 34396044, 2021). "Interestingly, tumour cell CDC42 has previously been shown to confer resistance to cytotoxic lymphocytes and, in breast cancer cells, CDC42-dependent actin remodelling at the immune synapse reduces killing by natural killer cells." (PMID 34374417, 2021). "Research has shown that Cdc42 activation promotes breast cancer cell migration." (PMID 32992837, 2020). "Therefore, as has been shown by us using mammosphere assays, Rac/Cdc42 inhibition can reduce stem cell-like growth in breast cancer." (PMID 32322580, 2020). "TNS1 modulated the activation of Cdc42 to regulate cell invasion in breast cancer." (PMID 32190687, 2020).
breast carcinoma (continued). "Altogether, this data suggests that the activation of Rac1 and Cdc42 is critical for breast cancer extravasation and metastatic colonization, and that ZINC69391 may provide a promising therapeutic option for aggressive breast cancer." (PMID 32992837, 2020). "Altogether, our work highlights a new, potentially druggable, molecular polarity feed-forward loop framework based on the interplay of TKS5, FGD1, and CDC42 function in the regulation of invadopodia activity as an essential axis of the MT1-MMP–based metastatic program of breast cancer cells." (PMID 32673397, 2020). "The overexpression of the MCF2L gene, encoding guanosine conversion factor, could activate the key regulatory factors of the Rho GTP family (Cdc42 and Rac1) and promote tumor metastasis in breast cancer cells." (PMID 32089682, 2020). "Furthermore, CD44 3′-UTR has a decoy effect that binds to miR-216a, miR-330 and miR-608 resulting in increased Cdc42 expression in MT-1 breast-carcinoma cells." (PMID 30754684, 2019). "Moreover, miR-224 can inhibit breast cancer cell invasion by directly suppressing Cdc42 during the interaction at their binding site." (PMID 30754684, 2019). "Interferon regulatory factor 4 binding protein (IBP, a Rho-family guanine nucleotide exchange factor for Rho family GTPases, including Rac1, RhoA and Cdc42) can mediate Rac1, RhoA and Cdc42 activation in breast cancer cells to regulate actin cytoskeleton rearrangement and MMP production." (PMID 30754684, 2019). "In addition, Cdc42 regulation via microRNAs provides new insights and potential approaches for breast cancer treatment." (PMID 30754684, 2019). "Cdc42 is one of these drug-resistant proteins involved in breast cancer." (PMID 30754684, 2019). "Besides phosphorylating Bcl-2 family members to protect breast cancer cells from intrinsic cell death, Cdc42 downstream effector PAK also regulates anti-cancer drugs-induced cell death." (PMID 30754684, 2019). "Unlike Ras, Rac and Cdc42 are not mutated in breast cancer, but activated via the deregulation of expression and/or activity of their upstream regulators, guanine nucleotide exchange factors (GEFs)." (PMID 31344865, 2019). "However, Cdc42 assists breast cancer cells in escaping apoptosis and chemotherapeutic treatments, allowing them to survive in circulation." (PMID 30754684, 2019). "Moreover, diabetes mellitus (DM), especially type 2 diabetes, has been recently regarded as a risk factor in breast cancer, due to the fact that high blood–glucose levels can stimulate EGFR activation and then trigger the EGFR/Cdc42 positive loop." (PMID 30754684, 2019). "Targeting Cdc42 also provides a strategy for precise breast cancer therapy." (PMID 30754684, 2019). "However, Cdc42 is often overexpressed in breast cancer cells and predominantly acts as a pro-tumor factor accompanied with the intricate downstream signaling transduction." (PMID 30754684, 2019). "However, c-Cbl is often compromised in breast cancer and the upregulation of Cdc42 activity is considered to impair c-Cbl activation, thus inhibiting EGFR degradation." (PMID 30754684, 2019). "Although the expression of Cdc42 is upregulated during breast cancer, it is not always mutated (approximately 0.1–1.7%)." (PMID 30754684, 2019). "Cdc42 mainly functions as an EGFR-signaling regulator in breast cancer cell proliferation." (PMID 30754684, 2019). "In addition to interacting with EGFR, Cdc42 has many other means of advancing breast cancer cell growth." (PMID 30754684, 2019). "To summarize, Cdc42 acts as a significant regulator in breast cancer cell migration and invasion." (PMID 30754684, 2019).
breast carcinoma (continued). "Another miR-29 family member, miR-29a, which also targets Cdc42 is downregulated in breast cancer." (PMID 30754684, 2019). "This selective inhibition of MBQ-167 may result from the different Cdc42-related GEF expression profiles in different types of breast cancer; MBQ-167 may only affect a subset of Cdc42-related GEFs that are activated in mesenchymal-like breast cancer cells." (PMID 30754684, 2019). "Ack1, as a downstream effector of Cdc42, has a significant role in promoting cell proliferation, migration, and invasion in a variety of human neoplasms such as hepatocellular carcinomas, breast cancers, and osteosarcomas." (PMID 29596304, 2018). "Alternatively, as for Rac1, CDC42 may play a as yet to be determined role in the nucleus that is active in breast cancer cells." (PMID 28451966, 2017). "In addition, CDC42, has also been shown to be down-regulated in breast cancer patients treated with metformin." (PMID 28423712, 2017). "Interestingly, Cdc42 over-expression has been described in breast cancer, lung cancer and cutaneous melanoma, and its up-regulation correlates with testicular cancer progression." (PMID 27341132, 2016). "High levels of Cdc42-interacting protein 4 (CIP4) in invasive breast cancer cells, such as in BLBCs, might offer an alternative means by which Cdc42 inhibits c-Cbl function." (PMID 23606532, 2013). "Cdc42 regulates key processes that are critical for mammary gland morphogenesis and become disrupted during the development, progression, and metastasis of breast cancer." (PMID 24074261, 2013). "Consequently, we highlighted Cdc42 as a downstream mediator of non‐canonical WNT‐5A signaling in breast cancer cells and suggest an essential role of Cdc42 activation in reducing breast cancer cell migration and invasion." (PMID 23727359, 2013). "RhoA, RhoB and Cdc42 protein expression was detected in all breast cancer cases." (PMID 23420497, 2013). "The aim of this study was to examine the expression of ERM (ezrin, moesin) and Rho (RhoA, RhoB and Cdc42) proteins in breast cancer (BC) patients and to investigate the relationship between the sub-cellular localisation of these proteins and clinicopathological characteristics and patient survival." (PMID 23420497, 2013). "Although our data explained in partly the mechanisms of IBP-mediated suppression of breast cancer cell apoptosis in response to cisplatin, whether this function is related to RhoGTPase (e.g. Cdc42) is still unknown." (PMID 22888789, 2012). "In addition, it was recently shown that FGD1, which is functionally related to FGD4, is up-regulated in human prostate and breast cancer, and regulates cancer cell invasion by modulating Cdc42 activation in a cell model." (PMID 22589722, 2012). "RhoA, Rac1, Cdc42, and other family members are overexpressed and hyperactivated in early and late stage human breast tumors, and elevated RhoA and Rac1 expression correlates with breast cancer progression." (PMID 20860838, 2010). "Rho GTPases including RhoA, Rac1, and Cdc42 are elevated and hyperactivated in breast cancer." (PMID 20860838, 2010). "Interestingly, Cdc42 overexpression in M231shN4C cells changed the cobblestone-like morphology to the slightly spindle-shaped morphology, indicating that Cdc42 overexpression in M231shN4C cells enhanced the mobility of breast cancer." (PMID 37149651, 2023). "Thus, we conclude that the unified model with the upstream effector motif and the feedback from Cdc42 to Rac1 can explain both the simultaneous dynamics of Cdc42 and Rac1 in the breast cancer cell line (MDA-MB-231) and the delayed activation in the MEF cell line." (PMID 37371108, 2023).
breast carcinoma (continued). "Rac/Cdc42 inhibitors also reduced tumor- infiltrating macrophages and neutrophils in tumors of mice treated with EHop-016, and macrophages and MDSCs from spleens and tumors of mice with breast cancer, including activated macrophages and monocytes, following MBQ-167 treatment." (PMID 37397366, 2023). "Overexpression of protein CDC42 in breast cancer could induce the signaling to TF BRCA1." (PMID 33802957, 2021). "This Cdc42 mutant may exist in breast cancer allowing it to overcome Fas-induced apoptosis." (PMID 30754684, 2019). "Furthermore, we found in MDA-MB-231 breast cancer cells that the inhibition of migration is mediated by the GPCR gastrin releasing peptide receptor (GRPR) leading to a reduced expression of migration regulating downstream targets like CDC42 and ROCK1." (PMID 31664083, 2019). "Consequently, IBP may regulate EMT and the movement of breast cancer cells via Rac1, RhoA and Cdc42 signaling pathways." (PMID 30754684, 2019). "However, mechanisms by which CDC42 might influence metformin response in breast cancer remain unknown." (PMID 28423712, 2017). "Therefore, one possibility is that CDC42 is also degraded in the nucleus, and its presence there in breast cancer could represent some deregulation of normal protein turnover." (PMID 28451966, 2017). "Moreover, the repression of Cdc42 is also found in HER2-positive breast cancer cells." (PMID 26783207, 2016). "In this study, we investigated the expression of the ERM (ezrin, moesin) and Rho (RhoA, RhoB, Cdc42) protein families in a homogeneous group of patients with stage II invasive ductal breast cancer (BC)." (PMID 23420497, 2013). "Since WASP-family proteins, Arp-2/3 as well as their upstream regulators (Rac1, Cdc42) are known to be overexpressed in several invasive cancers including breast cancer, protrusion of tumour cells may be much less sensitive to loss of Pfn1 expression compared to vascular endothelial cells." (PMID 17940506, 2007). "Distinct m6A circRNA methylation signatures were identified across breast cancer subtypes, with TNBC showing enrichment in pathways related to Wnt/β-catenin, CDC42 GTPase signaling, and cytoskeletal remodeling." (PMID 41516402, 2026). "Taken together, we conclude that when breast cancer cells experience cell swelling and osmotic stress, FGD3 activates Cdc42 and then ARP2/3 to induce lamellipodium formation at the cell border and loss of the internal stress fiber network." (PMID 41225536, 2025). "In breast cancer, PDLIM1 binds to α-actinin-4, activating CDC42 and promoting cell invasion and metastasis." (PMID 39548074, 2024). "GWASs have also demonstrated a genetic overlap between UL and breast cancer, particularly in the ER+ subtype, as well as with endometriosis, involving genes such as WNT4/CDC42, GREB1, ESR1, and follicle-stimulating hormone subunit beta (FSHB)." (PMID 38790186, 2024). "We also show that brain endothelial cells promote paracrine stimulation of mesenchymal-like morphology of breast cancer cells via DOCK4, DOCK9, RAC1 and CDC42." (PMID 38762624, 2024). "Gene expression levels of both CDC42 and ACTR2 were notably elevated in breast cancer tissues compared to their expression in normal tissues, and were ranked among the highest in terms of expression across various cancer types." (PMID 38612766, 2024). "Intriguingly, our analysis unveiled a significant correlation between a high CDC42 expression in tumor tissues and increased mortality rates in TNBC patients compared to all breast cancer patients." (PMID 38612766, 2024). "Recently, ARHGAP17, a Cdc42-specific GAP, was identified as a negative regulator of invadopodia in breast cancer cells by shRNA screening for Rho GAPs." (PMID 37482421, 2023). "Opposing correlations between CDC42 and CDC42BPA expression and OS are also seen in basal-like breast cancer." (PMID 37463901, 2023).
breast carcinoma (continued). "Label-free quantitative proteomic analysis of the proteome isolated from the MCF-7 breast cancer cell line, treated with 1 μM of doxorubicin, identified RAC1, CDC42, and RHOA GTPases that were inactivated by the ARHGAP1 protein." (PMID 37511111, 2023). "We found that upregulated Rho GTPases RAC1, CDC42, and RHOA participated in the TGF-beta signaling pathway in the breast cancer MCF-7 cell line treated with DOX." (PMID 37511111, 2023). "Results show a significant 60% decrease in MDSCs from mammary tumors of mice that received MBQ-167, which indicates an immunoprotective role for Rac/Cdc42 inhibitors." (PMID 37397366, 2023). "A dose-responsive drop in Rac1/Cdc42, WAVE2, phospho-Rac1/Cdc42, Arp2, and Arp3 was seen in MDA-MB-231 mammary tumor cells after 4 days of mangiferin therapy, in contrast to cells in respective control groups, according to a Western blot analysis." (PMID 38137424, 2023). "We have shown that OCT-1 knockdown suppresses the expression of the ARHGDIB, CAPZA2, PHACTR2, CDC42, XRCC5, and CAV1 genes, which is known to be increased in actively metastasizing breast cancer cells." (PMID 36143471, 2022). "Work in breast cancer cells extended this work by showing that GBP-2 inhibits cell migration and invadosome formation, accompanied by inhibition of Rac1 and activation of Cdc42 and RhoA." (PMID 35681772, 2022). "In breast cancer cells, DDR1 increases Cdc42 activation and its specific guanine nucleotide-exchange factor (GEF) Tuba." (PMID 35309920, 2022). "For example, SDCBP was found to modulate RhoA and Cdc42 expression via TGF-β1, which induced EMT and promoted breast cancer metastasis." (PMID 35155233, 2022). "A genomic and transcriptomic analysis by the Molecular Taxonomy of the Breast Cancer International Consortium (METABRIC) demonstrated that less aggressive, ER+ tumours were enriched for altered expression of genes in the CDC42 pathway." (PMID 35087170, 2022). "In breast cancer, a novel small molecule Rac1/Cdc42 dual inhibitor, MBQ-167, impaired STAT3 activation, resulting in decreased metastatic breast cancer cell migration." (PMID 32915198, 2020). "Our data demonstrate that the essential function of TKS5 in directing the formation of collagenolytic invadopodia in breast cancer cells requires FGD1, probably through the direct modulation of CDC42 activity." (PMID 32673397, 2020). "In contrast, the lncRNA MALAT1 has been found to serve as a ceRNA of the cell division cycle 42 (cdc42) 3′UTR, resulting in enhanced migration and invasion of breast cancer cells by binding miR-1 competitively." (PMID 32708601, 2020). "MALAT1 binds miR-1, miR-124, and miR-448, and acts as a ceRNA to reduce CDC42 and up-regulate CDK4 expression, leading to breast cancer cell cycle progression, cell migration, and invasion." (PMID 32174966, 2020). "By sponging miR-206, MALAT1 up-regulates ANXA2 and KRAS expression in gallbladder cancer cells, and reduces CDC42 and up-regulates CDK4 expression in breast cancer cells." (PMID 32174966, 2020). "The western blot results showed that miR-29a has a negative regulatory role regarding Cdc42 expression in MIN6 cells, which is similar to the findings for cancers such as nonsmall-cell carcinoma, stomach cancer, and breast cancer." (PMID 31662747, 2019). "All these data suggest that DAPT activates Cdc42 via PI3K/AKT signaling and then reduces the migration of breast cancer cells." (PMID 31057403, 2019).